CBX3 (chromobox 3)
Diseases named in the same sentence as CBX3 in open-access papers (continued):
Sharing a sentence is not in itself a finding about the gene and the disease.
gastric cancer (10 papers, 2021 to 2025). A primary or metastatic malignant neoplasm involving the stomach. "The microarray dataset revealed that upregulated mRNA expressions of CBX3 (HR = 0.59, P = 1.4E-09) caused better overall survival outcomes among gastric cancer patients." (PMID 35969177, 2022). "The CBX3 was shown to promote gastric cancer progression and was associated with chemotherapy and immunotherapy response." (PMID 34925377, 2021). "At the molecular level, CBX3 promotes gastric cancer cell proliferation and invasion by regulating the expression of cell cycle-related genes such as CCND1 and CDK4." (PMID 40175347, 2025). "CBX3 expression was upregulated in gastric cancer, and regulated the malignant phenotype of gastric cancer by mediating chemotherapy and immunotherapy response." (PMID 37436074, 2023). "By integrating the results of mRNA and protein expression levels, CBX3/4/8 expression levels increased significantly from clinical grade 1 to 2 in gastric cancer." (PMID 35969177, 2022). "CBX3 is also highly expressed in gastric cancer tissues and cell lines." (PMID 40175347, 2025). "CBX3 is a putative target of MYC and may serve as a new diagnostic biomarker and a potential target for immunotherapy in gastric cancer." (PMID 36304306, 2022). "Univariate and multivariate regression analyses revealed that CBX3, CBX8, age, gender, pT stage, pN stage, and pM stage were independent factors for the prognosis of gastric cancer patients." (PMID 35969177, 2022). "A prognostic gene model based on five CBX genes (CBX1, CBX2, CBX3, CBX7, and CBX8) predicted the overall survival of gastric cancer patients." (PMID 35969177, 2022). "The transcription levels of CBX2, CBX3, CBX4 and CBX5 were significantly enhanced, whereas the mRNA level of CBX7 was decreased in gastric cancer tissues compared with normal tissues." (PMID 34117289, 2021). "Moreover, we found a prognostic CBXs model comprising five genes (CBX1, CBX2, CBX3, CBX7, and CBX8) for gastric cancer patients." (PMID 35969177, 2022).
glioblastoma (10 papers, 2019 to 2025). The most malignant astrocytic tumor (WHO grade IV). "Further experiments showed that CBX3 was overexpressed in glioblastoma tissues and is a potential diagnostic and prognostic biomarker." (PMID 31138312, 2019). "Studies in glioblastoma showed that LINC00998 RNA directly interacted with chromobox 3 protein (CBX3) and prevented it from ubiquitin‐mediated degradation, suggesting that LINC00998 functions as a noncoding RNA." (PMID 36495128, 2023). "Past research reports have assessed the expression level and role of CBX3 in many tumors, including glioblastoma and gastric cance." (PMID 35573019, 2022). "We confirmed that CBX3 was overexpressed in glioblastoma by immunohistochemical analysis of tissue microarrays and qPCR analysis of surgical specimens." (PMID 31138312, 2019). "CBX3 mRNA expression was evaluated by qPCR in glioblastoma cell lines, including SF268, U373, U251, U87MG, U118, and A172 cells." (PMID 31138312, 2019). "To determine the effects of CBX3 on glioblastoma cell growth, we monitored proliferation using the CCK8 assay." (PMID 31138312, 2019). "In our study, CBX3 was upregulated in glioblastoma, and patients with high CBX3 expression had shorter survival." (PMID 31138312, 2019). "Moreover, CBX3 Knockdown was found to impedes the proliferation of cancer cells in glioblastoma by stagnating the cell cycle during G2/M cell cycle transition." (PMID 35573019, 2022). "We found that compared to differentiated glioblastoma cells (DGC), expression of CBX2, CBX3, and CBX5 were upregulated, while CBX1, CBX4, CBX6, CBX7, and CBX8 were downregulated." (PMID 39988672, 2025). "Summarily, based on our comprehensive analysis about the expression, clinicopathological parameters, and prognostic values of different CBXs, only CBX3 and CBX8, which got consistent results on all these aspects, were identified as likely to take a critical part in the development of glioblastoma." (PMID 35210369, 2022). "Conclusively, based on our comprehensive analysis of the expression, clinicopathological parameters, and prognostic values of eight CBX members, CBX3 and CBX8 were identified and might play pivotal roles in the tumorigenesis and progression of glioblastoma." (PMID 35210369, 2022).
tongue squamous cell carcinoma (10 papers, 2018 to 2023). A squamous cell carcinoma that arises from the tongue. "Zhang etal. showed that CBX3/HP1γ is upregulated in tongue squamous cell carcinoma and negatively impacts prognosis by delaying the G1/S phase via p21 downregulation, which promotes tumor proliferation." (PMID 31375643, 2019).
ovarian carcinoma (7 papers, 2020 to 2024). A malignant neoplasm originating from the surface ovarian epithelium. "High expression levels of CBX1 and CBX3 were significantly associated with chemotherapy resistance in ovarian cancer patients." (PMID 32742466, 2020). "For CBX3, improved expression of CBX3 mRNA was associated with unfavorable OS in women with grade II ovarian cancer." (PMID 32742466, 2020). "In the present study, we analyzed the effects of circ_0061140 in the progression and PTX sensitivity of ovarian cancer in vitro and in vivo, and demonstrated whether the mechanism underlying the sensitivity of ovarian cancer involved circ_0061140/miR-136/CBX3 pathway." (PMID 34649611, 2021). "Recently, some researchers found that high expression of CBX3 promoted ovarian cancer cell proliferation and was significantly related to unfavorable progression and chemoresistance, impacting the treatment outcomes of OV patients." (PMID 36292141, 2022). "Significant down-regulation of CBX1 and CBX7 was found in ovarian cancer (OV) tissues compared to normal tissues, while the expression levels of CBX3 were significantly up-regulated in OV tissues." (PMID 35155439, 2022). "Cell experiments were conducted to explore the role of CBX3 in the proliferation of ovarian cancer cells." (PMID 35155439, 2022). "The results from these two datasets both presented that treatment with the platinum drugs upregulated the expression level of CBX3 expression in ovarian cancer tissues or cells." (PMID 35155439, 2022). "Next, we conducted CCK8 assay and the results showed that compared with siCtrl group, the growth of ovarian cancer cells was inhibited after transfected with siCBX3, suggesting that CBX3 was involved in the proliferation of ovarian cancer cells." (PMID 35155439, 2022). "Upregulation of CBX3 mRNA was obviously involved in worse prognosis for all ovarian cancer patients and in patients who were treated with Taxol, platin, and Taxol+platin chemotherapy." (PMID 32742466, 2020). "Subsequently, IHC analysis found that CBX1, CBX2 and CBX3 expression was significantly higher in ovarian cancer tissues than in the corresponding controls." (PMID 32742466, 2020). "In stage I and II ovarian cancer patients, the upregulated CBX3 mRNA level was a reliable factor for predicting poor PFS but not OS." (PMID 32742466, 2020). "CBX3 promoted ovarian cancer cell proliferation and impacts the treatment outcomes of OV patients." (PMID 35155439, 2022). "Further cell experiments also showed that CBX3 promoted the proliferation of ovarian cancer cells." (PMID 35155439, 2022). "Nevertheless, the prognostic value of CBX3 in ovarian carcinoma is unclear." (PMID 32742466, 2020). "A growing number of studies have verified that CBX3 has an essential impact on prognosis and that CBX3 may participate in the carcinogenesis of ovarian cancer." (PMID 32742466, 2020). "Thus, further cell experiments were conducted to explore the function of CBX3 in OV, and the results showed that CBX3 could promote ovarian cancer cell proliferation and impact the treatment outcomes of OV patients." (PMID 35155439, 2022). "Thus, we further investigated the function of CBX3 in ovarian cancer cells." (PMID 35155439, 2022). "Furthermore, we explored the effect of CBX3 on the treatment outcomes of ovarian cancer patients." (PMID 35155439, 2022). "To investigate the impact of CBX3 on the proliferation of ovarian cancer cells, we conducted CCK8 assay to analyze the growth of ovarian cancer cells which were transfected with CBX3 siRNA (siCBX3) or siRNA control (siCtrl)." (PMID 35155439, 2022). "The knockdown efficiency was evaluated and the results showed that compared with siCtrl group of two ovarian cancer cell lines including SKOV3 and HO8910, the expression of CBX3 was decreased in siCBX3 group in both protein and mRNA levels." (PMID 35155439, 2022).
ovarian carcinoma (continued). "Specifically, high expression levels of CBX1, CBX2 and CBX3 all predicted unfavorable OS and PFS in all ovarian cancer patients." (PMID 32742466, 2020). "Furthermore, upregulation of CBX3 expression was strongly correlated with poor OS in stage III and IV ovarian cancer patients." (PMID 32742466, 2020). "Interestingly, the results showed that high expression of CBX3 was significantly related to a positive PFS in women with clinical stages III and IV ovarian cancer." (PMID 32742466, 2020). "However, elevated CBX3 mRNA expression was irrelevant to OS both in patients with grade I and grade III ovarian cancer." (PMID 32742466, 2020). "Furthermore, elevated expression of CBX3 was not related to PFS in all grades of patients with ovarian cancer." (PMID 32742466, 2020).
melanoma (6 papers, 2019 to 2026). A malignant, usually aggressive tumor composed of atypical, neoplastic melanocytes. "Cbx3/HP1γ-deficient mice were equally effective in reducing B16 melanoma and NB-9464 NBL tumor burden, leading to their increased survival compared to controls." (PMID 34721405, 2021). "RT-qPCR assays demonstrated that Ccl2/Ccr2 and Cxcl9/Cxcl10/Cxcr3 levels were higher in B16 melanoma tumors from Cbx3/HP1γ-deficient mice than those from controls." (PMID 34721405, 2021). "More cleaved caspase 3 (CC3) was detected in B16 melanoma tumor cells co-cultured with Cbx3/HP1γ-deficient CD8+ effector T cells compared to control co-cultures." (PMID 34721405, 2021). "Treatment with Cbx3/HP1γ-deficient CD8+ effector T cells alone resulted in a statistically significant decrease in B16 melanoma and NBL tumor burden compared to treatment with control cells." (PMID 34721405, 2021). "Compared to controls, Ccr10 and Cxcl12/Cxcr4 levels were decreased in B16 melanoma tumors from Cbx3/HP1γ-deficient mice." (PMID 34721405, 2021). "Genetic ablation of Prf1 in Cbx3/HP1γ-deficient animals led to uncontrolled B16 melanoma growth and decreased TUNEL positivity indicative of reduced tumor-cell apoptosis while NBL tumor burden was incompletely inhibited and tumor-cell death was readily detected." (PMID 34721405, 2021). "Expression of Ifng, Gzmb and Prf1 was elevated in B16 melanoma and NBL tumors excised from Cbx3/HP1γ-deficient mice compared to controls or Cbx3/HP1γTg animals." (PMID 34721405, 2021). "TUNEL staining revealed more apoptotic tumor cells (brown) in melanoma and NBL tumors from Cbx3/HP1γ-deficient mice compared to controls." (PMID 34721405, 2021). "Prf1 and Gzmb levels in melanoma tumors from control and compound mutant mice as well as those treated with Cbx3-Il21r- or Il21r-deficient CD8+ effector T cells were low compared to Cbx3/HP1γ-deficient mice." (PMID 34721405, 2021). "In a prospective cohort of LUAD and melanoma patients, CTCs co-expressing CBX3 and GPX4 were selectively elevated in the blood samples of metastatic cases compared to the non-metastatic group, highlighting the clinical association between ferroptosis-resistant CTCs and metastatic progression." (PMID 41540451, 2026). "Thus, the ability of Cbx3/HP1γ-deficient CD8+ T cells to eradicate solid tumors was evaluated using the mouse ID8 or MOSE-LTICv ovarian, B16 melanoma and NB-9464 NBL tumor models." (PMID 34721405, 2021). "Melanoma and NBL growth proceeded unchecked in tumor-bearing B6.SJL congenic mice treated with control, Il21r-/- or Cbx3-Il21r-deficient CD8+ effector T cells compared to animals receiving Cbx3/HP1γ-deficient CD8+ effector T cells." (PMID 34721405, 2021). "Within B16 melanoma tumors, there was an enrichment of transferred Cbx3/HP1γ-deficient CD8+NKG2D+ effector T cells, not transferred control or endogenous CD8+ effector T cells." (PMID 34721405, 2021). "Our data underscore the fact that LEF-1 and IL-21R are requisite for the persistence of Cbx3/HP1γ-deficient CD8+ effector T cells in tumors with varied mutation loads that are ICB responsive (B16 melanoma) or non-responsive (ovarian and NBL)." (PMID 34721405, 2021).
liver cancer (5 papers, 2018 to 2022). An epithelial or non-epithelial malignant neoplasm that arises from the liver. "High CBX3/HP1γ expression was associated with unfavorable prognosis in liver cancer." (PMID 31375643, 2019). "In the present study, we used bioinformatics analysis to examine the expression and prognostic significance of CBX3/HP1γ in patients with different cancers, including liver cancer." (PMID 31375643, 2019). "CBX3/HP1γ expression was compared in liver cancer and normal liver tissues in the following six datasets from the Oncomine and TCGA databases: Roessler Liver 2, Chen Liver, Roessler Liver, Guichard Liver, TCGA, and Wurmbach Liver." (PMID 31375643, 2019). "In order to confirm the expression and function of CBX3/HP1γ in liver cancer, multiple bioinformatics analyses were conducted." (PMID 31375643, 2019). "Higher mRNA expression of CBX3 was also significantly related with unfavorable OS of liver cancers patients and was an independent prognostic factor for shorter OS of liver cancer patients, which indicated that CBX3 took part in the tumorigenesis of HCC." (PMID 30481161, 2018). "Here, we performed a bioinformatics analysis using the Oncomine, TCGA and Human Protein Atlas databases, the Kaplan-Meier plotter, and the UALCAN web-portal to explore the expression and prognostic significance of CBX3/HP1γ in patients with different cancers, including liver cancer." (PMID 31375643, 2019). "CBX3/HP1γ mRNA expression was elevated in liver cancer tissues compared to normal tissues." (PMID 31375643, 2019). "CBX3 expression in liver cancer and normal liver tissues was verified using the UALCAN database." (PMID 31375643, 2019).
cervical cancer (4 papers, 2019 to 2022). A primary or metastatic malignant neoplasm involving the cervix. "Suppression of CBX3 expression had an inhibitory effect on cervical cancer cell growth, demonstrating that CBX3 might be an effective therapeutic target for cervical cancer." (PMID 32742466, 2020). "Analysis of GEO profiles (GDS2416) in 33 different biopsies from 16 cervical cancer patients showed a negative correlation between the expression of UBE2L3 and CBX3 (a gene encoding HP1γ), whereas the expression of UBE2L3 and CBX1 (a gene encoding HP1β) showed a positive correlation." (PMID 32203172, 2020).
esophageal squamous cell carcinoma (3 papers, 2020 to 2022). Esophageal squamous cell carcinoma (ESCC) is a type of esophageal carcinoma (EC) that can affect any part of the esophagus, but is usually located in the upper or middle third.
lymph node metastasis (3 papers, 2020 to 2021). "For clinicopathological features, high expression of CBX3 was associated with lymph node metastasis (OR = 2.96, 95% CI 1.42-6.20) and lager tumor size (OR = 1.60, 95% CI 1.12-2.28)." (PMID 33273987, 2020). "In our analysis of clinicopathological data, the high expression of CBX3 was indeed associated with larger tumor size and lymph node metastasis in cancer patients." (PMID 33273987, 2020). "The results revealed that a high expression level of CBX3 was apparently related to lymph node metastasis (N+ vs. N0, OR = 2.96, 95% CI 1.42-6.20, P = 0.004); further sensitivity analysis showed that this result was reliable." (PMID 33273987, 2020). "To further clarify the roles of CBX3, CBX5, and CBX7 in disease progression, we use the UALCAN database to analyze CBX expression in different patients with different disease grades and lymph node metastasis status." (PMID 34966411, 2021).
malignant glioma (3 papers, 2020 to 2023). A grade III or grade IV glioma arising from the central nervous system. "Previous research has linked elevated CBX3 expression to poor outcomes in lung, gastric, and ovarian malignancies; however, a study has also shown that CBX3 expression can have a tumor-suppressive effect in malignant glioma." (PMID 37674204, 2023). "However, a study has also shown that the expression of CBX3 can mediate the tumor suppression effect of lncRNA LINC00998 in malignant glioma." (PMID 34395271, 2021).
neuroblastoma (3 papers, 2017 to 2025). Neuroblastoma (NB) is the most common solid, extracranial childhood tumor. "Cbx3/HP1γ deficiency releases the effector capacity of CD8+ T cells to control neuroblastoma (NBL) growth." (PMID 34721405, 2021). "Ovarian and neuroblastoma are tumors with low mutation rates that respond minimally to ICB, yet their growth is effectively controlled by Cbx3/HP1γ-deficient CD8+ effector T cells." (PMID 34721405, 2021).
acute myeloid leukemia (2 papers, 2022). Acute myeloid leukemia (AML) is a group of neoplasms arising from precursor cells committed to the myeloid cell-line differentiation. "The expression of CBX3 was increased in 28 tumor tissues but merely decreased in acute myeloid leukemia (LAML)." (PMID 35573019, 2022).
cutaneous melanoma (2 papers, 2022). A primary melanoma arising from atypical melanocytes in the skin. "Six tumors exhibiting the greatest relationship between the expression of CBX3 and the extent of immune cell infiltration were chosen for additional analysis, including BRCA, COAD, LUSC, cutaneous melanoma (SKCM), THYM and UCEC." (PMID 35573019, 2022).
diffuse large B-cell lymphoma (2 papers, 2022). "LINCRNA-00857 promotes lymphomagenesis and proliferation rate via miR-370-3p-CBX3 cascades in diffuse large B-cell lymphoma." (PMID 35779530, 2022). "A previous study showed that LINC00857 serves as an ceRNA that positively regulates CBX3 by negatively regulating miRNA370 expression, which promoted diffuse large B-cell lymphoma proliferation and lymphomagenesis." (PMID 35418193, 2022).
gastric intestinal type adenocarcinoma (2 papers, 2020 to 2021). An adenocarcinoma of the stomach arising on a background of intestinal metaplasia. "Chen's gastric dataset revealed that CBX3 was overexpressed in gastric mixed adenocarcinoma (fold − change = 1.998 and P = 1.62E − 07) and gastric intestinal-type adenocarcinoma (fold − change = 1.878 and P = 1.13E − 16)." (PMID 33344640, 2020). "Moreover, CBX3 was overexpressed in gastric intestinal-type adenocarcinoma (fold − change = 3.014 and P = 6.64E − 14) in D'Errico's gastric dataset and GC (fold − change = 1.736 and P = 6.79E − 04) of Wang's gastric dataset." (PMID 33344640, 2020).
kidney cancer (2 papers, 2022 to 2023). Primary or metastatic malignant neoplasm involving the kidney. "We also collected and analyzed gene expression data from 33 kidney cancer cell lines and observed that CBX3 was expressed similarly across all cell lines." (PMID 37674204, 2023). "The analysis of the CCLE datasets revealed that CBX3 was substantially expressed in kidney cancer cell lines." (PMID 37674204, 2023). "The cancerSEA database investigation revealed a positive correlation between CBX3 expression and tumor stemness in kidney cancer." (PMID 37674204, 2023). "Furthermore, angiogenesis and stemness were positively correlated with CBX3 expression in kidney cancer." (PMID 37674204, 2023).